STAT3 (signal transducer and activator of transcription 3)
Diseases named in the same sentence as STAT3 in open-access papers (continued):
Sharing a sentence is not in itself a finding about the gene and the disease.
cancer (continued). "STAT3 appears constitutively active in a broad variety of cancers that often become addicted to its activity." (PMID 33718197, 2021). "Despite these different mechanisms underpinning radioresistance in different types of cancer cells with active STAT3, targeting STAT3 was an effective approach to overcome radioresistance." (PMID 34830176, 2021). "We found that the expression of STAT3 in cancer tissues was significantly abnormally upregulated (P < 0.01)." (PMID 34712324, 2021). "MEK inhibitors were previously reported to induce “compensatory” STAT3 activation in other cancer cells." (PMID 34102002, 2021). "Signal transducers and activators of transcription 3 (Stat3) are considered an important regulator of VEGF expression in cancer." (PMID 33445558, 2021). "The STAT3/5 regulation by PRL observed in this study supports previous studies showing activation of these transcription factors in different types of cancer cells and the effect is cell-dependent." (PMID 34358244, 2021). "Data presented here extensively expands upon this work and provides further insights into the relationship of STAT3 and Ref‐1 in multiple cancer types." (PMID 33274592, 2021). "Under normal aerobic conditions, PP suppresses the mitochondrial electron transport chain complex I and inhibits cancer cell proliferation via the JAK/STAT3 signaling pathway." (PMID 34950627, 2021). "Niclosamide, a dual inhibitor of STAT3 and mTOR, was selected not only because of its efficacy against cancer and its synergistic effects with many other drugs; but because the mTOR pathway is parallel to STAT3–NF-κB axis." (PMID 34223559, 2021). "Given its ability to transform cells when constitutively activated and due to its over-expression in a wide range of human cancers, STAT3 is currently considered as an oncogene." (PMID 34141616, 2021). "Excessive activation of EGFR activates multiple downstream signaling pathways, such as the MEK/ERK/MAPK, PI3K/AKT/mTOR, and JAK1/STAT3/5 signaling pathways), thereby enhancing the tumorigenesis, progression, and metastasis of various cancers." (PMID 33909822, 2021). "Here, we show that Stattic exerts many STAT3-independent effects on cancer cells, calling for reassessment of results previously ascribed to STAT3 functions." (PMID 33839684, 2021). "As aberrant activation of STAT3 signaling pathways contributes to many diseases including cancer, we further explored the role of HsA on STAT3 activation in HCC cells." (PMID 33947048, 2021). "STAT3 further stimulated the production of cytokines, forming a positive feedback loop that promoted cancer stem cell self‐renewal." (PMID 33463006, 2021). "Previous studies have shown that IL-6 augments cancer chemotherapeutic resistance through activation of the NF-κB κ and STAT3 signaling pathways." (PMID 34131122, 2021). "Constitutively-activated STAT3 has been reported to contribute to cancer proliferation and metastasis." (PMID 33805945, 2021). "Second, it functions as a direct STAT3i with proven STAT3-related therapeutic activity in cancer patients with advanced systemic disease when used orally as part of bioavailable formulations accompanied by low toxicity and reversible mild side-effects." (PMID 35056076, 2021). "IL-11 induces Signal transducer and activator of transcription 3 (STAT3) phosphorylation and increases the expression of anti-apoptotic protein Bcl-2 and Survivin in cancer cells." (PMID 34503172, 2021). "Our data indicated that BUB1 not only mediated cancer cell mitosis but also contributed to transcriptional activation of STAT3 signaling in BCa cells." (PMID 34852826, 2021). "Meanwhile, activated STAT3 is also responsible for high metabolic activities to provide an environment for the survival of malignant tumors." (PMID 34611143, 2021).
cancer (continued). "The aberrant TGF-β signaling in cancer cells leads to an increased epithelial signal transducer and activator of transcription 3 (STAT3) activity, resulting in increased ECM fibrosis." (PMID 34094963, 2021). "It was previously reported to acquire enlarged polyploid nuclei and block Stat3 phosphorylation by inhibiting Aurora A in various cancer cell lines." (PMID 34715887, 2021). "Among them, STAT3 is tyrosine phosphorylated, transcribed after activation, and with constitutive activity in various cancers." (PMID 34641334, 2021). "Recently, numbers of studies have shown roles for activated JAK/STAT3 signaling in the regulation of metastasis and proliferation in cancers." (PMID 34365903, 2021). "With 10 identifiers, we observed that these genes interacted with stemness genes such as SOX-2 and NANOG, genes important in cancer pathways such as STAT3, CTNNB1, EGFR, TNF, and CASP3, and immune genes such as IL2 and CD4." (PMID 34685742, 2021). "Particularly, STAT3 protein is involved in cancer progression, metastasization, and drug resistance, thus, its inhibition can represent an interesting strategy for increasing cancer chemotherapy sensitivity." (PMID 34771097, 2021). "The reported anti-cancer effects of butein are due, at least in part, to the potent inhibition of STAT3 phosphorylation." (PMID 35008855, 2021). "Various studies suggest STAT3 expression is elevated in tumors relative to normal tissues and its long-term activation correlates with development of various cancers." (PMID 34760885, 2021). "IL-6 upregulation in Gprc5a-knockout mice is identified to explain the promoted metastasis of cancer, in which IL-6 activates the STAT3 signaling pathway and induces the recruitment of MDSC to promote lung metastasis." (PMID 34689842, 2021). "Piceatannol shows an anti-cancer activity by exerting repressive effects on multiple cellular factors, such as mTOR and STAT3." (PMID 34575983, 2021). "The therapeutic potential of gambogic acid against cancer has been determined by its abrogative effects on NF-κB and STAT3 signaling, leading to apoptosis and anti-angiogenesis." (PMID 34575983, 2021). "We showed that butein anti-cancer effects are due, at least in part, to a potent inhibition of STAT3 phosphorylation, leading to PARP cleavage and consequently cell death." (PMID 35008855, 2021). "Gefitinib (Iressa) is a tyrosine kinase inhibitor of epidermal growth factor receptor (EGFR) kinase, but gefitinib resistance resulting from activation of STAT3 signaling has been reported to occur in cancer patients." (PMID 33392396, 2021). "Tris DBA decreased the viability of both types of cancer cell lines (HCC and MM) and caused a pronounced inhibition of STAT3 activation." (PMID 34771643, 2021). "For example, miR-155 and miR-21 are mostly upregulated in myeloid-derived suppressor cells (MDSCs), and promote immunosuppressive effects via activation of the STAT3 pathway in cancer cells." (PMID 34846108, 2021). "On the other hand, cancer cells overexpressing STAT3 demonstrated increased expression of V-ATPase, reduced sensitivity to bafilomycin A treatment, impaired ROS generation, and facilitated anoikis resistance." (PMID 34234852, 2021). "Here, we focus on the role of HMGA2 in the biology of TNBC and demonstrate a link between HMGA2-mediated cancer phenotypes and regulation of NF-kB/IL-6/STAT3 signaling." (PMID 34680349, 2021). "The majority of reports concerning the STAT3 focus on the regulation of genes involved in cancer and inflammation, and its transcriptional activity is mostly studied in the context of its aberrant upregulation and activation." (PMID 34685476, 2021). "CLDN9 is an HCC proto-oncogene that increases the invasiveness and migration capability of cancer cells by affecting the STAT3 signaling pathway." (PMID 33686959, 2021).
cancer (continued). "The benzo[b]thiophene 1,1-dioxide (BTP) moiety is a characteristic pharmacophore of many potent STAT3 inhibitors, markedly enhancing the ROS level and exhibiting antiproliferative activity in cancer cells." (PMID 33946916, 2021). "Several studies have highlighted both the extreme anticancer effects of Cryptotanshinone (CT), a Stat3 crippling component from Salvia miltiorrhiza, as well as other STAT3 inhibitors to fight cancer." (PMID 33544704, 2021). "Taken together, these results support that LLL12B is an excellent STAT3 inhibitor candidate for cancer therapy." (PMID 33753770, 2021). "The activation of a signal transducer and activator of transcription 3 (STAT3) signaling pathway is present in a wide range of solid cancers and drug-resistant cancers in humans." (PMID 33946916, 2021). "Another antiapoptotic factor found in prostate is STAT-3; it helps in the induction of cancer in prostate." (PMID 35069196, 2021). "Although STAT3 as an important target for cancer therapy has been well documented, it is a challenge to develop potent and specific STAT3 inhibitors." (PMID 33491667, 2021). "Recently, it was shown that IL-6 secreted by human and murine PSCs stimulated STAT3-dependent cancer cell survival, migration, and metastasis." (PMID 34440697, 2021). "Increasing emphasis is being placed on developing direct STAT3 inhibitors for clinical application and some clinical trials in advanced cancer are ongoing." (PMID 34302498, 2021). "IL-6 cooperates with TNF-α also in stimulating the Janus kinase (JAK)-signal transducer and activator of transcription (STAT), the JAK2/STAT3 pathway, which is involved in inflammation, cancer progression, muscle mass wasting, and cancer-related cachexia." (PMID 34684523, 2021). "By silencing STAT3, cancer resistance to doxorubicin, cisplatin, and paclitaxel can be re-sensitized." (PMID 34577615, 2021). "Still, studies in liver cancer confirmed that TQ strongly suppressed the phosphorylation of STAT3 associated with decreased JAK activity, thus enhancing the apoptotic death rate of cancer cells." (PMID 35010954, 2021). "Multiple signaling pathways, including the transforming growth factor beta (TGF-β), Wnt, Notch, signal transducer and activator of transcription 3 (STAT3), and PI3K/AKT, have been linked to cancer metastasis." (PMID 34589421, 2021). "This complex elevates phosphorylated STAT3 (p-STAT3) expression and activates nuclear translocation-induced effector genes, contributing to inflammation, immune reactions, and cancer oncogenesis and development." (PMID 33855091, 2021). "Kymera therapeutics last year began two phase I clinical trials examining KT-474 (targeting IRAK4) and KT-333 (targeting STAT3) candidates to treat autoimmune diseases and patients with cancer, respectively." (PMID 34685679, 2021). "For instance, IL6 induces numerous cancer-promoting changes through STAT3, while IL27 or OSM can induce an opposing effect through the related signal transducer STAT1, also activated as part of the JAK/STAT pathway." (PMID 34834425, 2021). "STAT3 is a transcription factor and regulates various aspects of BC, such as cancer onset, progression, proliferation, metastasis, and chemoresistance." (PMID 34298771, 2021). "The reduction in cancer metastasis was associated with regulating the PI3K/AKT, MAPK/ERK, and STAT3 pathways—central CSC-associated inflammatory signaling cascades." (PMID 34950252, 2021). "Given its important roles in cancer, STAT3 has been recognized as an attractive cancer therapeutic target." (PMID 33391507, 2021). "A very direct way to test this is to apply a drug, or drugs, that can inactivate STAT3’s actions, and determine rates of death of those cancer cells reliant on high levels of STAT3." (PMID 33544704, 2021). "This aligns with the literature supporting that IL-6 and its activation of STAT3 counteracts the effects of radio- and chemotherapy in many cancers." (PMID 35087822, 2021).
cancer (continued). "The STAT3 signal is activated in various human malignant tumors and participates in the progression of many cancer cell types." (PMID 34535085, 2021). "High CD44 levels have also been discovered as a marker for cancer stem cells in many other solid malignant tumors, modulating intracellular pathways via protein interactions and STAT3 signal transduction." (PMID 34067416, 2021). "Nevertheless, recent studies suggest that STAT3 signaling contributes to metabolic reprogramming in cancers." (PMID 34887764, 2021). "We explained that RIPK4 is an effective gene for inhibiting HCC metastasis and exerts a cancer suppressing effect by inhibiting the STAT3 pathway, as demonstrated by wound healing, Transwell and Western blotting experiments." (PMID 34222329, 2021). "We prospect that targeting both CREPT and STAT3 will be a promising intervention for cancer therapy." (PMID 33531691, 2021). "IL-6 has been reported to activate STAT3 to promote EMT through the induction of Snail expression in cancers." (PMID 34771643, 2021). "HES1 has been involved in promoting cancer cell transformation and increasing chemoresistance by an enhancement in the STAT3 transcriptional activity 47-49." (PMID 33390847, 2021). "STAT3 is a key regulator of cell proliferation, survival and apoptosis and is constitutively activated in most human cancers including prostate, pancreas, breast cancers and leukaemia." (PMID 34294140, 2021). "IL-6 is another key cytokine, secreted by cancer cells, immune cells and CAFs, which inhibits apoptosis of cancer cells through STAT3 activation." (PMID 34503172, 2021). "Phosphorylated STAT3 (pSTAT3) is strictly involved in cellular plasticity processes that imply the coexistence of cancer stem cells (CSCs) and the EMT." (PMID 35047557, 2021). "Our extensive findings are in line of the other report demonstrating that cancer patients with STAT3 SNP rs1053004 TT genotype expressed lower STAT3 protein as detected by Western blotting when compared to those with CC genotype." (PMID 34307193, 2021). "Inhibition of AKT signal prevented cancer cells proliferation, while inhibition of the STAT3 signal reverted drugs resistance and cancer migration induced by kynurenine." (PMID 33842334, 2021). "Accumulating evidence reveals that IFN-γ is a known mediator of PD-L1 expression through the transcription factor STAT3 in human cancer cells, leading to suppression of antitumor immune responses." (PMID 34440920, 2021). "At the same time, ROS accumulation activates the IL-6/STAT3 pathway, which is often hyperactive in cancer." (PMID 34070716, 2021). "STAT3 signaling hyperactivation occurs in most human cancers and is connected with a poor prognosis." (PMID 34177924, 2021). "The mechanisms of action of this drug against cancer, bacterial, viral, and metabolic diseases include uncoupling of oxidative phosphorylation and modulation of Wnt/β-catenin, NF-κB, STAT3, mTORC1, and Notch signaling pathways." (PMID 34755820, 2021). "In an in vivo model, IL-6 secretion from MDSC endows cancer cell stem-cell-like properties by activating the IL-6/STAT3 signaling pathway." (PMID 34689842, 2021). "Meanwhile, overexpression of IL22 protects NSCLC cancer cell lines from chemotherapy-induced apoptosis via activation of STAT3, which triggers the expression of downstream anti-apoptotic proteins including BCL2 and BCL-xL." (PMID 34944848, 2021). "The available literature on curcumin and JAK/STAT in cancer mainly look at how curcumin inhibits phosphorylation of various JAKs and namely STAT3 and STAT5." (PMID 34867402, 2021). "In cancer metastasis, a biological process similar to trophoblast invasion, IL-17 has been shown to promote migratory capacity to cancer cells via the STAT3 pathway." (PMID 34790194, 2021).
cancer (continued). "Aberrant activation of STAT3 signaling is observed in numerous cancers and promotes the development and progression of cancers." (PMID 33909202, 2021). "According to previous literature reports, cancer cell migration can be inhibited by blocking of STAT3 pathway." (PMID 33909625, 2021). "In cervical cancer, the EMT process of cancer cells was regulated through the JAK2/STAT3 signaling pathway." (PMID 33788424, 2021). "IL-6 can regulate the crosstalk between CSCs and cancer cells through constitutive activation of Stat3, and plays an important role in the formation of mammospheres." (PMID 33804152, 2021). "An important component of STAT3 oncogenic activity resides in the induction of aerobic glycolysis, making cancer cells highly sensitive to glucose deprivation, whereas they are protected from apoptosis and senescence." (PMID 33718197, 2021). "Various molecular pathways are able to enhance cancer progression and stemness that include STAT3, NF-κB, Wnt/β-catenin signaling and Sonic Hedgehog, among others." (PMID 34769099, 2021). "In FGFR-overexpressing cancer cells, tyrosine phosphorylation of STAT3 is also dependent on the concomitant FGFR-dependent activity of SRC and JAK2 kinase." (PMID 34439322, 2021). "Nevertheless, application of curcumin in combination with EGCG (50 mg/kg per day) in a mouse model of colorectal carcinoma led to suppression of JAK/STAT3 signalling in endothelial cells and thereby their recruitment by cancer cells." (PMID 34834295, 2021). "And qRT-PCR findings additionally showed that multiple endogenous STAT3 target genes including cyclin D1and survivin, many of which are crucial in cancer cell proliferation and survival, were substantially downregulated by oxelaidin." (PMID 33980886, 2021). "The sites of the interconnection of the NF-κB, Nrf2 and STAT3 signaling pathways and aberrations in their activation mechanisms make it possible to use them as targets in cancer cells for potential chemotherapeutic compounds." (PMID 34443375, 2021). "STAT3 pathway was found to be hyperactivated in many cancers, and aberrant activation generally means a poor clinical prognosis." (PMID 33982666, 2021). "S1P has been found to play an essential role in maintaining persistent activation of STAT3 in cancer cells." (PMID 33781742, 2021). "STAT3 has been a protein target due to its roles in the progression of cancer development, stemness, chemoresistance, and radioresistance." (PMID 33660414, 2021). "Because STAT3 regulates genes that promote cancer cell survival, proliferation, and invasion, we next tested mRNA expression changes of previously established STAT3 target genes, BCL2L1, BIRC5, CCND1, and MMP9 after short-term Olaparib exposure." (PMID 34956861, 2021). "In consistent with one recent study, we found that STAT3 is a potential target of FBP1 in cancer cells." (PMID 34363022, 2021). "Overexpression of Pin1 in cervical cancer can increase nuclear retention of NF-κB and promote transactivation of STAT3, further promoting the occurrence of cancer 144-146." (PMID 33537091, 2021). "For example, mechanistic targets of rapamycin (mTOR) and signal transducer and activator of transcription 3 (STAT3) play a role in the maintenance and proliferation of healthy and cancer stem cells." (PMID 34884848, 2021). "When the STAT3 signal, known to be essential for cancer cell proliferation, is activated, cytoplasmic STAT3 protein moves to the nucleus through the nuclear inner membrane where emerin is present." (PMID 34206382, 2021). "The interest started in the contest of cancer research, focusing on finding molecules able to interact and inhibit the transcriptional activity of STAT3, which is known to regulate cell growth and apoptosis and is constitutively active in various cancers." (PMID 34642818, 2021). "IL-8 can reduce PTEN expression via phosphorylation to stimulate STAT3 signaling, resulting in enhanced cancer progression." (PMID 33670518, 2021).